SIK3 (SIK family kinase 3)
Description:
Positive regulator of mTOR signaling that functions by triggering the degradation of DEPTOR, an mTOR inhibitor. Involved in the dynamic regulation of mTOR signaling in chondrocyte differentiation during skeletogenesis. Negatively regulates cAMP signaling pathway possibly by acting on CRTC2/TORC2 and CRTC3/TORC3 (Probable). Prevents HDAC4 translocation to the nucleus (By similarity).
Synonyms: SIK-3; KIAA0999; QSK; L19; FLJ12240; SEMDK
Tractability: Small molecule: a structure with a bound ligand is known; a high-quality ligand is known; it belongs to a druggable protein family. PROTAC: it is named in the literature on targeted protein degradation; ubiquitination databases record sites on it; its protein half-life has been measured; a small molecule that binds it is known.
Target class: CAMK protein kinase group; CAMK protein kinase CAMK1 family; Protein Kinase; Kinase; Enzyme; CAMK protein kinase QIK subfamily
Chemical probes: GPLG3970 (high quality), HG-9-91-01 (high quality), MRIA9 (high quality), YKL-05-099
Gene: Protein-coding gene on chromosome 11 (116,843,402 to 117,098,445, reverse strand). Ensembl gene ENSG00000160584.
Subcellular location: Cytoplasm
Gene Ontology:
Molecular function: ATP binding; magnesium ion binding; protein binding; protein serine kinase activity; protein serine/threonine kinase activity; tau-protein kinase activity; protein kinase activity
Biological process: positive regulation of TORC1 signaling; positive regulation of TORC2 signaling; protein phosphorylation; intracellular signal transduction; microtubule cytoskeleton organization
Cellular component: cytoplasm
Genetic constraint (gnomAD): Loss-of-function variants: 28 observed, 143.03 expected, observed/expected ratio (o/e) 0.2, 90% interval 0.14 to 0.27. The upper end of that interval is the gene's LOEUF score, 0.27, which puts it in group 1 of 6, group 1 being the genes least tolerant of losing a copy. Missense variants: 1,312 observed, 1,765.5 expected, observed/expected ratio (o/e) 0.74, 90% interval 0.71 to 0.78. Synonymous variants: 681 observed, 678.99 expected, observed/expected ratio (o/e) 1, 90% interval 0.94 to 1.07.
Homologues: Orthologues: macaque SIK3 (99% identical), chimpanzee SIK3 (96% identical), rabbit SIK3 (95% identical), pig SIK3 (95% identical), dog SIK3 (93% identical), mouse Sik3 (91% identical), rat Sik3 (91% identical), guinea pig SIK3 (88% identical), tropical clawed frog sik3 (67% identical), zebrafish sik3 (47% identical), Caenorhabditis elegans C27D6.11 (8% identical), Caenorhabditis elegans Y38H8A.4 (8% identical), and 1 more. Paralogues in human: SIK2 (25% identical), SIK1 (22% identical), BRSK1 (15% identical), BRSK2 (14% identical), SNRK (14% identical), NUAK2 (13% identical), HUNK (13% identical), NUAK1 (13% identical), PRKAA2 (12% identical), PRKAA1 (12% identical), MELK (12% identical), NIM1K (11% identical), and 5 more.
Diseases named in the same sentence as SIK3 in open-access papers:
SIK3 is named in the same sentence as 61 diseases in open-access papers, as found by Europe PMC text mining. Sharing a sentence is not in itself a finding about the gene and the disease. The quoted sentences say what the papers report.
breast carcinoma (15 papers, 2017 to 2025). "SIK3 expression is elevated in breast cancer cells and is associated with poor survival rates in breast cancer patients." (PMID 39063214, 2024). "SIK3 may mediate ABCB1-associated drug resistance in breast cancer cells." (PMID 31762812, 2019). "Researchers used a combination of emodin and berberine to significantly inhibit SIK3 activity and reduce the proliferation of breast cancer cells." (PMID 39063214, 2024). "The combination activity of berberine and emodin on this kinase was evaluated on MCF-10A, MCF-7, and MDA-MB-231 cells, as high SIK3 expression in breast cancer cells contributes to tumor formation." (PMID 34073059, 2021). "Berberine, the most known quaternary protoberberine alkaloid (QPA), has been reported to inhibit the SIK3 protein connected with breast cancer." (PMID 34943140, 2021). "Expression of the gene coding protein SIK3 is connected with breast cancer, and berberine combined with emodin can inhibit this protein." (PMID 34943140, 2021). "SIK3 expression is increased in the presence of salt and interleukin-17, leading to breast cancer cell proliferation." (PMID 31888295, 2019). "Previous phosphoproteomics based data from our laboratory demonstrated an enhanced expression and phosphorylation of SIK3 in breast cancer cells following high salt treatment." (PMID 29861863, 2018). "Our initial studies have demonstrated an enhanced expression of SIK3 in high salt passaged MCF-7s breast cancer cells." (PMID 29861863, 2018). "In these studies the authors have demonstrated that SIK3 upregulates expression of cyclinD and E. In agreement with these findings, our current studies demonstrate an enhanced G1/S phase cell cycle in breast cancer cells." (PMID 28658303, 2017). "To further determine if the SIK3 expression can be induced in other breast cancer cell lines, we have tested five breast-derived cell lines." (PMID 28658303, 2017). "We show that the metastasis specific inflammatory molecules are specifically upregulated by SIK3 in breast cancer cell lines." (PMID 28658303, 2017). "Taken together, these data suggest that SIK3 is a critical downstream factor specifically upregulated in breast cancer cells following co-stimulation with high salt and IL-17." (PMID 28658303, 2017). "We have recently demonstrated that prostratin, a small molecule identified in the tea from the bark of Somoan tree and extensively studied in HIV research, induced a cytotoxic effect specifically on high salt treated breast cancer cells potentially through SIK3 inhibition." (PMID 29861863, 2018). "While our current experiments were limited to breast cancer studies, we think the mechanisms of SIK3 signaling might be related to all solid tumors." (PMID 28658303, 2017). "Emodin in combination with berberine significantly inhibits salt-inducible kinase 3 (SIK3) activity, reducing cell growth and inducing cell cycle arrest and apoptosis in breast cancer cells." (PMID 40490812, 2025). "High salt exposure activates salt-inducible kinase-3 (SIK-3), a key regulator of mitogenic activity, while nuclear factor of activated T cells 5 (NFAT5) signaling upregulates VEGF expression in breast cancer cells, thereby facilitating cancer metastasis." (PMID 39944693, 2025). "Our phosphoproteomic analysis identified a unique molecular target, salt-inducible kinase-3 (SIK-3), that is specifically upregulated in breast cancer cells following high-salt treatment." (PMID 34064273, 2021). "SIK3 has been reported to be overexpressed in high salt/IL-17 environments and mediate cell proliferation, inflammation and metastasis in MCF-7 breast cancer cells." (PMID 31762812, 2019).
breast carcinoma (continued). "Furthermore, knockdown of SIK3 with siRNA (specificity of siRNA to silence SIK3 is demonstrated in latter section) has reduced the cell proliferation by upto 25%, supporting our previous claim that co-treatment of high salt with IL-17 induces upregulation of breast cancer cell proliferation." (PMID 28658303, 2017). "In addition, emodin combined with berberine significantly inhibited the activity of salt-inducible kinases 3 (SIK3), belonging to the AMPK-related kinases, which elevated expressions in breast cancer cells contributing to tumorigenesis." (PMID 34502424, 2021). "A similar increase in SIK3 expression was observed in other breast cancer cell lines, MDA-MB-231, BT20, and AU565, while non-malignant breast epithelial cell line, MCF10A, did not induce SIK3 expression under similar conditions." (PMID 28658303, 2017).
ovarian cancer (11 papers, 2015 to 2025). A primary or metastatic malignant neoplasm involving the ovary. "UBE2G2 is a mutant gene in human leukemia and SIK3 has been recently identified as a tumor antigen associated with ovarian cancer tumorigenesis." (PMID 27494850, 2016). "By Cox regression model analysis, clinicopathological parameters including age, stage, histologic types, residual tumor, CA125 expression, SIK3 expression, optimal debulking surgery, early-stage ovarian cancer, and high SIK3 expression were independently associated with better OS." (PMID 31762812, 2019). "Although we have observed in vitro that SIK3 is important for ovarian cancer growth, the associations between SIK3 and chemoresistance-associated proteins i.e., ABC proteins, as well as clinical survival in ovarian cancer, are still largely unknown." (PMID 31762812, 2019). "SIK3 is known to be associated with breast, hepatocellular, and ovarian cancer." (PMID 31888295, 2019). "Likewise, SIK3 has been documented as a putative tumour-associated antigen with expression in 55% of ovarian cancer samples, and, like SIK2, can control cell cycle progression at the G1/S checkpoint." (PMID 26068970, 2015). "Because SIK3 functions have been reported to be associated with glucose tolerance/energy metabolism 31,32, further studies may be needed to our current observation, identify the regulation of ABCG2 in EOC as well as glycolytic activity/metabolic change in SIK3-associated ovarian cancer." (PMID 31762812, 2019). "However, the association between SIK3 expression and patient outcomes in ovarian cancer remains unclear." (PMID 31762812, 2019). "Conversely, SIK3 demonstrates a dual role: it promotes cell proliferation in breast and ovarian cancers by facilitating the G1/S transition, but inhibits proliferation in non‐small cell lung cancer (NSCLC) through modulation of AP1 and IL6 signaling." (PMID 39877288, 2025). "In our previous study, we found that knocking down the salt-inducible kinase 3 (SIK3) gene in an ovarian cancer cell line triggers the upregulation of IL-1β and TNF-α genes and increases the release of proinflammatory cytokines." (PMID 38203391, 2023). "The misregulation of Sik2 and Sik3 being detected in several cancer cases at both genetic and epigenetic levels, and Sik3 being established as an ovary cancer marker are consistent with our finding that Siks can promote tumorigenesis." (PMID 32542037, 2020). "Ovarian cancer cells with SIK3 knockdown display increased chemoresistance to Taxol plus cisplatin treatment, which is associated with the upregulation of the ABCG2 transporter." (PMID 31762812, 2019). "In our study, ovarian cancer cells with SIK3 knockdown and ABCG2 upregulation showed significant chemoresistance to Taxol/cisplatin treatment." (PMID 31762812, 2019). "Recently, we identified a novel tumor-associated antigen, salt-inducible kinase 3 (SIK3), during tumorigenesis in ovarian cancer." (PMID 31762812, 2019). "In our cohort, we observed that most of the patients with high expression levels of SIK3 and CA125 had stage III disease (45.6% for SIK3 and 67.3% for CA125) and serous-type ovarian cancer (46.8% for SIK3 and 70.1% for CA125)." (PMID 31762812, 2019). "SIK1, SIK2 (QIK) and SIK3 (QSK) have been reported to have a role in metastasis in gastric ADCs and mitotic progression in prostate and ovarian cancers." (PMID 26196184, 2015). "In light of these findings, it is suggested that combinations of biomarkers with SIK3 would aid prognosis and that SIK3 could also provide the substrate for new therapeutic applications in ovarian cancer." (PMID 36731029, 2023). "Indeed, we found that stage III/IV ovarian cancer patients with high expression of SIK3 are more chemosensitive than patients with low expression of SIK3 (P=0.01, Fisher's exact test)." (PMID 31762812, 2019). "It has been reported that the expression of SIK3 is related to ovarian cancer development." (PMID 31170924, 2019).
ovarian cancer (continued). "Therefore, ovarian cancer cells with SIK3 knockdown displayed significant chemoresistance to cisplatin and Taxol compared to control cells." (PMID 31762812, 2019). "Serial sections of paraffin-embedded serous-type ovarian cancer lesions were used to detect ABCG2 and SIK3 protein levels by immunohistochemistry." (PMID 31762812, 2019). "From our in vitro studies, we found that the ovarian cancer cell lines SKOV3 and OVCAR4 with SIK3 knockdown displayed significant chemoresistance to Taxol/cisplatin, which was specifically associated with the upregulation of ABCG2." (PMID 31762812, 2019). "Regarding the sensitivity and specificity analyses of these markers for prognostic prediction, tissue expression of SIK3 showed better specificity than tissue and serum expression of CA125 (80.0%, 56%, and 50%, respectively) by IHC in ovarian cancer patients." (PMID 31762812, 2019). "To explore the mechanism of SIK3 suppression-induced chemoresistance in ovarian cancer, we performed microarray analysis in two SKOV3 cell lines with SIK3 knockdown (shSIK3#01 and #61)." (PMID 31762812, 2019). "ARN-3261 preferentially targets SIK2 and SIK3 (IC50 of 11 and 19 nM, respectively) and has been shown to sensitize ovarian cancer cell lines and xenografts to carboplatin and is currently in Phase 1a/1b clinical trials in patients with ovarian, peritoneal and other solid tumors." (PMID 36731029, 2023). "From our previous study, we identified SIK3 as a novel ovarian TAA that is highly and preferentially expressed in ovarian cancer but not in benign gynecologic diseases, i.e., adenomyosis or endometriosis, with elevated CA125 levels." (PMID 31762812, 2019).
Obesity (8 papers, 2012 to 2025). Accumulation of substantial excess body fat. "Furthermore, genetic variations in SIK3 have been associated with dyslipidaemia and obesity in humans." (PMID 27807598, 2017). "In humans, studies have shown that the expression and activity of SIK2 and SIK3 are downregulated in the adipose tissue of individuals with obesity." (PMID 40384110, 2025). "A critical question is how the reduced SIK2 and SIK3 expression in obesity impacts adipose tissue physiology." (PMID 27807598, 2017). "In summary, we have demonstrated that SIK2 and SIK3 are downregulated in human obesity and insulin resistance." (PMID 27807598, 2017). "Sik3, Apoa1, and Apoc3 have been shown to be associated with variations in total, HDL, LDL-cholesterol or triglyceride levels, and Cadm1 with obesity-related traits." (PMID 26555648, 2015). "Moreover, Sik3 is an essential gene that is broadly expressed in mouse brain neurons, whereas Sleepy mutant mice also display other developmental phenotypes, such as obesity and reproductive defects (Funato H and Yanagisawa M, unpublished)." (PMID 35667851, 2022).
dyslipidemia (6 papers, 2012 to 2025). "Although the association of SNPs in SIK3 with dyslipidemia is well documented, the functional relevance of these variants in lipid metabolism is yet to be established." (PMID 40384110, 2025). "SNPs in the human SIK3 gene have been reported to be associated with dyslipidemia in genome-wide associated studies." (PMID 40384110, 2025). "Variants in well-known triglyceride-related genes such as BUD13 and SIK3 are known to be associated with triglyceride levels, lipid traits, overall lipid homeostasis, or metabolic syndrome." (PMID 33763119, 2021). "Also, rs180365 (LINC02702‐BUD13), rs964184 (ZPR1), rs662799 (ZPR1), rs10750097 (novel APOA5), rs6589574 (APOA1), rs562179 (novel SIK3), associated with lipid‐related traits and/or metabolic syndrome, showed evidence of interaction with TSS of APOA1." (PMID 40665476, 2025). "All but four of the mapped genes (SIK3, SIDT2, UBASH3B, and CUX2) had been previously reported to be associated with metabolic syndrome, as indicated by a keyword search of “metabolic syndrome” in the GWAS catalog." (PMID 30382898, 2018). "Given the severe phenotype caused by CA feeding, we surmised that cholestasis might be the primary phenotype of Sik3−/− mice, and this may then lead to or enhance the other phenotypes, e.g., lipodystrophy and dyslipidemia." (PMID 22662228, 2012). "The relation of the individual SNPs, including those on SIK3, SIDT2, UBASH3B, and CUX2, to metabolic syndrome was further examined by single-SNP–multi-trait analysis, adjusted for age and sex." (PMID 30382898, 2018).
lipodystrophy (5 papers, 2012 to 2024). A congenital or acquired disorder characterized by abnormal loss or redistribution of the adipose tissue in the body. "The survived adult Sik3 knockout mice show lipodystrophy phenotypes with altered cholesterol and bile acid metabolism in the liver, indicating the involvement of SIK3 in lipid metabolism." (PMID 39081779, 2024). "Sik3−/− mice have a malnourished the phenotype (i.e., lipodystrophy, hypolipidemia, hypoglycemia, and hyper-insulin sensitivity) accompanied by cholestasis and cholelithiasis." (PMID 22662228, 2012). "Sik3-/- mice display lipodystrophy, hypolipidemia, hypoglycemia, and hyper-insulin sensitivity." (PMID 31978080, 2020). "Adiponectin had been found to promote fat accumulation in adipose tissues and to improve insulin sensitivity in leptin-resistant mice, which could explain the hypoglycemic phenotype of Sik3−/− mice, but not their lipodystrophy." (PMID 22662228, 2012).
diabetes (4 papers, 2015 to 2025). "This gene encoding SIK family kinase 3, is also biologically relevant to glucose metabolism, and is a potential target for diabetes therapeutics." (PMID 35769078, 2022). "Although SIKs (SIK1, SIK2, and SIK3) have shown critical roles in multiple contexts of physiology and participate in distinct human diseases, such as cancer, diabetes, colitis, and sepsis, the role of SIKs in psoriasis is poorly understood." (PMID 39959414, 2025).
Hypoglycemia (4 papers, 2012 to 2020). A decreased concentration of glucose in the blood. "Sik3−/− mice show reduced energy storage, which is associated with hypoglycaemia and hyper-insulin sensitivity." (PMID 25060954, 2014). "Once the Sik3−/− mice were supplied exogenously with an energy source, such as lactate (lactate tolerance test), they were able to produce glucose efficiently, suggesting that the hypoglycemia of Sik3−/− mice may be due to a lack of energy storage followed by an enhanced insulin response." (PMID 22662228, 2012).